MMP2 (matrix metallopeptidase 2)
Diseases named in the same sentence as MMP2 in open-access papers (continued):
Sharing a sentence is not in itself a finding about the gene and the disease.
myocardial infarction (continued). "MMP2 was chosen not only for its similarity to MMP9 in terms of size and functionality, but also because MMP2 and MMP9 are closely related collagenases and involved in the turnover of the ECM after myocardial infarct." (PMID 36140171, 2022). "On the other hand, doxycycline could not reduce scar thinning and compensatory LV hypertrophy, despite having decreased MMP-2 and MMP-9 activity in a model of acute myocardial infarction with LV dysfunction." (PMID 35893744, 2022). "In rats with myocardial infarction, DHI treatment improved cardiac remodeling and preserves ventricular function by suppressing the expressions of TGF-β1 and fibrosis-related proteins (MMP-2 and MMP-9)." (PMID 33456666, 2020). "Here, we investigated the effect of decreased AMF on oxidative stress marker matrix metalloproteinase-2 (MMP-2) and its influence on the fate and homing and paracrine character of MSCs after IC or intramyocardial cell delivery in a closed-chest reperfused myocardial infarction (MI) model in pigs." (PMID 29670878, 2018). "GBE could inhibit experimental rat myocardial remodeling after acute myocardial infarction via reduced transcription of TGF-β1, MMP-2 and MMP-9 genes and by the decreased expression of type I collagen, MMP-2 and MMP-9 proteins in myocardial cells." (PMID 26268459, 2015). "Although this hypothesis should be further demonstrated, previous reports have demonstrated that intracoronary administration of adult stem cells induces the downregulation of metalloproteinases in myocardium (MMP2 and MMP9) after myocardial infarct." (PMID 25964098, 2015). "Greater understanding of the mechanisms that govern MMP-2 activity may lead to the development of new therapeutic strategies aimed at preservation of the contractile function of the heart subjected to myocardial infarction (MI) or I/R." (PMID 24455428, 2013). "A dual-isotope radiolabeled MMP-2/9 ACPP (previously named dACPP, in this paper referred to as ACPP-2/9) approach recently proved valuable in the discrimination between intact and activated probe in in vivo biodistribution studies in mouse models of cancer and myocardial infarction." (PMID 26147581, 2015). "MMP-2 and MMP-9 were studied for their roles in left ventricular remodeling and postmyocardial infarction prognosis since they are activated within the myocardial tissue after MI." (PMID 31205590, 2019).
liver cancer (80 papers, 2010 to 2025). An epithelial or non-epithelial malignant neoplasm that arises from the liver. "High levels of MMP2/9 are associated with increased metastasis and poor prognosis in liver cancer patients." (PMID 35840921, 2022). "MMP-2 is overexpressed in breast, gastric, and liver cancers and promotes metastasis of tumor cells." (PMID 40133252, 2025). "IL-17 promotes liver cancer cell migration and invasion by increasing the levels of IL-8, MMP2, and VEGF, while TNF-α exacerbates liver cell injury and apoptosis via the NF-κB pathway." (PMID 40308492, 2025). "The occurrence, development, and immune escape mechanism of liver cancer are closely related to the production of sMICA/B mediated by MMP2 and MMP9." (PMID 40563539, 2025). "They reached the same conclusion that HIF-1α can promote the progression of liver cancer by affecting MMP2 and MMP9." (PMID 40563539, 2025). "FAK deletion inhibited liver cancer metastasis by reducing the expression and activity of matrix metalloproteinase 2 (MMP-2) and matrix metalloproteinase 9 (MMP-9)." (PMID 38560575, 2024). "MMP-2, -7 and -9 have been confirmed to play important roles in migration and invasion of liver cancer cells." (PMID 35890125, 2022). "The results indicated that ASIC1α can up-regulate the expression of MMP-2/9 to enhance the migration, invasion, and proliferation of liver cancer cells via the PI3K/AKT/mTOR pathway." (PMID 35840921, 2022). "Since MMP-2/9 plays an important role in the migration and invasion of liver cancer cells and is highly expressed in liver cancer cells, we explored the relationship between ASIC1α and MMP-2/9." (PMID 35840921, 2022). "Inhibition of the PI3K/AKT/mTOR pathway reduced the expression level of MMP-2/9 and inhibited the migration, invasion, and proliferation of liver cancer cells." (PMID 35840921, 2022). "Overexpression of MMP-2/9 and activation of AKT reversed these effects on liver cancer cells caused by inhibition of ASIC1α." (PMID 35840921, 2022). "Overexpression of HOXD-AS1 competitively binds miR-130a-3p and prevents SOX4 miRNA-mediated degradation, thereby activating the expression of EZH2 and MMP2, and promoting liver cancer metastasis." (PMID 35706002, 2022). "On the other hand, most importantly, decreased expression of MMP-2/9 inhibited the migration and invasion of liver cancer cells." (PMID 35840921, 2022). "We conclude that ASIC1α can regulate migration, invasion, and proliferation of liver cancer cells through the MMP-2/9/PI3K/AKT/mTOR pathway." (PMID 35840921, 2022). "At present, anti-CD147 monoclonal antibody can inhibit the invasion ability of liver cancer by reducing the expression of MMP2 and MMP9." (PMID 35003362, 2021). "HOXD-AS1 was bound to miR-130a-3p in a competitive manner, which activated the expression of EZH2 and MMP2 and facilitated liver cancer metastasis." (PMID 34987577, 2021). "Abnormal expressions of MMP2/MMP9 were often observed in tumor tissues or cancer cell lines and were associated with tumor metastasis in many cancers including liver cancer." (PMID 31988091, 2020). "Matrix metalloproteinases (MMPs) are major hydrolytic enzymes degrading almost all ECM components and the basement membrane, and previous studies have suggested that MMP2/MMP9 were closely associated with the invasion and metastasis of liver cancers." (PMID 31988091, 2020). "In our study, we found that PP2 treatment in liver cancer cells suppressed cell migration and invasion, accompanied by downregulated expression of MMP2/MMP9, suggesting they were responsible for the suppression effect of PP2." (PMID 31988091, 2020). "Clinically, overexpression of MMP-2 are considered to be involved in improved metastasis and poor diagnosis in liver cancer patients." (PMID 32376896, 2020).
liver cancer (continued). "Previous study has reported associations between high expression of MMP2 or MMP9 and tumor aggressiveness in liver cancer." (PMID 30591064, 2018). "In liver cancer, MMP-2 and -9 expression and activities were upregulated and downregulated by recombinant N-terminal of Sonic Hedgehog (SHH) and the SHH signaling inhibitor." (PMID 24944688, 2014). "Administration of HIF-1α inhibitors can block the upregulation of MMP2 and delay the progression of liver cancer, providing further verification of the conclusion that the HIF-1α/MMP2 or HIF-1α/MMP9 signaling pathways are involved in the occurrence and development of liver cancer." (PMID 40563539, 2025). "Indeed, it has been shown that tumor-infiltrating Th17 cells promote liver cancer cell migration by increasing the levels of MMP2 and MMP9 in an NF-κB dependent manner." (PMID 37958417, 2023). "In addition, IL-17 promotes liver cancer cell migration and invasion by increasing the levels of IL-8, MMP2, and VEGF." (PMID 37958417, 2023). "Our findings indicated that PPP-LIP nanocarriers could be a promising tumor-targeted medication delivery strategy for treating liver cancers with elevated MMP2 expression." (PMID 36104946, 2022). "A previous study underlined the clinical potency of the MMP activation concept, particularly MMP-2, as a strategy to generate safer oncolytic viruses for the treatment of primary and secondary liver cancers and GBM without loss of potency." (PMID 36366531, 2022). "Whether ASIC1α can inhibit the migration, invasion, and proliferation of liver cancer by inhibiting MMP-2 and MMP-9 via the PI3K/AKT/mTOR pathway is unknown." (PMID 35840921, 2022). "Inhibition of ASIC1α expression also can inhibit migration and invasion of liver cancer cells; so, whether ASIC1α and MMP-2/9 are correlated has interested us." (PMID 35840921, 2022). "MMP2 is one of the most studied MMPs, whose families are overexpressed in liver cancer." (PMID 34007838, 2021). "GPx3 inhibits tumor invasion by inhibiting the JNK-Cjun-MMP2 pathway in liver cancer." (PMID 34926458, 2021). "Moreover, the mucin 15- (MUC15-) and MT1-MMP- (MMP14-) encoding genes are significantly related to capsule formation in liver cancer through the regulation of MMP2 expression." (PMID 34007838, 2021). "Moreover, after Mettl3 knockdown in liver cancer cells, Western blot analysis validated that Mettl3 knockdown decreased the protein level of Snail, MMP2, MMP9, and FN1, but increased that of E-Cad, in both HepG2 and MHCC97H cells." (PMID 32483411, 2020). "In previous study, we found that BMP-2 silence could inhibit liver cancer cell’s proliferation, migration and invasion by down-regulation of MMP2 and MMP9 through MAPK/ERK pathway." (PMID 27886213, 2016). "We hypothesize that activation of the MMP2 signaling pathway may promote the proliferation, invasion and metastasis of the liver cancer cells, thus affecting the prognosis of HCC." (PMID 25013467, 2014). "In previous study, we found that BMP-2 could promote liver cancer cell’s proliferation and migration, and played an important role in liver cancer invasion through down-regulation of MMP2 and MMP9." (PMID 25002834, 2014). "Interestingly, in this study, bufalin also could increase the expression of MMP3, an essential protein in regulating cell migration, which is in contrast to another study that showed bufalin reduced the levels of MMP2/9 in liver cancer HCCLM3 and HepG2 cells." (PMID 37860119, 2023). "At the same time, Western blot results showed that, compared to the control group, the ApoM gene deletion group had a higher level of MMP-2 protein expression whereas the overexpression group had a lower level, suggesting that the ApoM gene inhibited the migration and invasion of liver cancer cells." (PMID 34149930, 2021).
liver cancer (continued). "In the current study, silencing of FASN, FSCN1 or SPTBN1 expression in liver cancer cells led to changes in the mRNA expression of EMT-associated markers, E-cadherin, N-cadherin, vimentin and transcription factors Snail and Twist, and altered the protein expression of MMP-2 and MMP-9." (PMID 32699531, 2020). "In addition, OPE exhibited anti-migration and anti-invasion effects on liver cancer cells, which might be related to decreased expression of MMP-2 and MMP-9." (PMID 32021647, 2020). "Overexpression of EIF5A2 can induce EMT to promote liver cancer cell metastasis, and silencing of EIF5A2 can enhance the sensitivity to 5-fluorouracil (5-FU) in liver cancer cells by blocking the p38 MAPK and JNK/c-Jun/MMP-2 signaling pathways." (PMID 40964657, 2025). "Further, we knocked down or overexpressed CREB5 in a mouse liver cancer cell line Hep1-6 and found that CREB5 promoted EMT and increased the expression of MMP2 and MMP9 in Hep1-6 cells." (PMID 39915455, 2025). "Under the combined action of GM-CSF and oxidative stress, the protein expression of MMP-2 and MMP-9 in liver cancer cells was significantly increased, and the inhibitory effect of SHP-1 was insignificant." (PMID 38644382, 2024). "Further, gold nanostructures were functionalized with matrix metalloproteinase-2 (MMP-2) and pay loaded with IR820 for synergistic therapies (PTT-PDT) for liver cancer." (PMID 36839754, 2023). "We further demonstrated that ASIC1α up-regulates MMP-2/9 via activation of the PI3K/AKT/mTOR pathway, thereby promoting migration, invasion, and proliferation of liver cancer cells." (PMID 35840921, 2022). "For example, in pancreatic and liver cancers under irradiation, fibroblasts increase the secretion of various humoral factors including cytokines such as bFGF, TNF-a, VEGF, IL-6, EGF, MMP-2, and MMP-9." (PMID 35089951, 2022). "In this systematic review, only one in vivo study (10%) reported a decrease in the levels of MMP-2 and MMP-9 in liver cancer after treatment with carvacrol, the majority 8.6% (n = 6) were in vitro studies." (PMID 34305611, 2021). "Similar with their findings, we proved that Fascin-1 knockdown decreased MMP2 and MMP9 expression, and increased Sorafenib sensitivity in liver cancer cells." (PMID 34897283, 2021). "First, according to the western blot experiment, the expression of Cyclin D1, MMP2, and MMP9 decreased significantly, indicating that the overexpression of miR-141 can inhibit the proliferation, migration, and invasion of liver cancer cells." (PMID 34675977, 2021). "In our study, we also evaluated the influence of Fascin-1 on MMP2 and MMP9 expression in liver cancer cells." (PMID 34897283, 2021). "We further revealed inhibited liver cancer cell migration and invasion through suppressed cofilin activity, as well as downregulation of the AKT/NF-κB signaling pathway resulted in a decrease MMP-2/MMP-9 expression by PP2 treatment." (PMID 31988091, 2020). "The CXCR3-A isoform bound by CXCL9 upregulates MMP2 and MMP9 expression, and promotes invasion and metastasis of CD133(+) liver cancer cells." (PMID 31623313, 2019). "In pulmonary adenocarcinoma and liver cancers, decreased expression of ANXA2 after ANXA2 knock-down was followed by decreased expression of MMP2, as well as decreased proliferation, migration and invasion ability." (PMID 31210752, 2019). "On the other hand, in vivo experiments using a rodent model of liver cancer demonstrated that LDM treatment with cisplatin resulted in reduced levels of VEGF and MMP-2." (PMID 30344920, 2018). "Rd has been shown to inhibit migration of liver cancer cell lines HepG2 by reducing expression of MMP-1, MMP-2 and MMP-7." (PMID 24130681, 2013). "MMP2, MMP9 and MMP13 proteins play significant roles in liver cancer invasion and migration." (PMID 39744479, 2025).
liver cancer (continued). "In liver cancer cells, cytoplasmic region of GP73 can interact with epithelial-mesenchymal transition (EMT)-related substrates such as matrix metalloproteinase-2 (MMP-2) and MMP-7, promoting their secretion into extracellular spaces and enhancing cancer invasiveness." (PMID 39845976, 2024). "Previous research has suggested that the Wnt signaling might promote the expression of MMP-2 and MMP-9 in liver cancer." (PMID 38468952, 2024). "SHP-1 inhibited the protein expression of MMP-2 and MMP-9 in liver cancer cells." (PMID 38644382, 2024). "In addition to the EMT regulated by Snail, nuclear Snail was also reported to play an another key role in regulating cell invasion by inducing increases in MMPs, such as MMP-1, MMP-2, MMP-7, MMP-9, and MMP-14, in ovarian, oral, and liver cancers." (PMID 36766694, 2023). "Overall, the inhibition of MMP-2/-9 and the balance between MMP-2/-9 and TIMP-1/-2 could play a critical role in liver cancer therapy." (PMID 35155196, 2021). "Furthermore, Fascin-1 knockdown suppressed MMP-2 and MMP-9 expression, impaired actin cytoskeleton rearrangement, inactivated Hippo/YAP signaling, and increased Sorafenib sensitivity in liver cancer cells." (PMID 34897283, 2021). "To determine how GP73 facilitates cell invasion, we analysed the expression of secretory proteins in the exosomes of five different normal or liver cancer cell lines (R2 = 0.948) and confirmed that secretory GP73 (sGP73) correlated positively with cytosolic MMP‐2." (PMID 30677226, 2019). "In the study, CXCR3-A isoform that was bound by CXCL9 was found to cause significant change of ERK1/2 phosphorylation level in the MAPK signaling pathway, consequently upregulating the MMP2 and MMP9 expression and promoting invasion and metastasis of CD133+ liver cancer cells." (PMID 26883105, 2016). "By comparing the expression of MMP2 in fibrolamellar carcinoma with that in HCC, it was found that the pathogenesis and biological behavior were different in different histological types of liver cancer." (PMID 25013467, 2014). "Thus, the question can be asked of whether ASIC1α regulates the expression of MMP-2/9 through the PI3K/AKT signaling pathway and thereby affects the migration, invasion, and proliferation in liver cancer cells." (PMID 35840921, 2022). "However, PtoxPdp as a dithiocarbamate derivative repressed MMP-2, and MMP-9 expression in the liver cancer cell line was first observed, this indicated that the structural unit of podophyllotoxin introduced to dithiocarbamate did not alter action pattern in regulation of MMPs." (PMID 31557166, 2019). "In this study, the mRNA expression of integrins and MMPs that was detected in different liver cancer cell lines and MHCC97H cells was found to feature low levels of integrin α5 mRNA expression and high levels of integrin αv, integrin β1, integrin β3, MMP1, MMP2 and MMP9 mRNA expression." (PMID 20939933, 2010). "However, the relationship between ASIC1α and MMP-2 and MMP-9 in liver cancer cells has not been elucidated." (PMID 35840921, 2022). "In addition, we propose that MMP‐2 is not the only trafficking substrate of GP73 because the knockdown of GP73 strongly inhibits cell proliferation and invasion of liver cancer cell lines, which implies that not only the trafficking of MMP‐2 is inhibited." (PMID 30677226, 2019).